ATXN2L (ataxin 2 like)
Description:
Involved in the regulation of stress granule and P-body formation.
Synonyms: A2D; A2LG; A2LP; A2RP
Tractability: Antibody: UniProt places it where antibodies can reach, with high confidence. PROTAC: UniProt records ubiquitination sites on it; ubiquitination databases record sites on it; its protein half-life has been measured.
Gene: Protein-coding gene on chromosome 16 (28,822,999 to 28,837,237, forward strand). Ensembl gene ENSG00000168488.
Subcellular location: Membrane; Cytoplasm; Nucleus speckle; Cytoplasmic granule
Subcellular location (Human Protein Atlas): Cytosol
Gene Ontology:
Molecular function: cadherin binding; protein binding; RNA binding
Biological process: mRNA metabolic process; stress granule assembly
Cellular component: cytoplasmic stress granule; cytosol; membrane; nuclear speck; cytoplasm
Genetic constraint (gnomAD): Loss-of-function variants: 24 observed, 113.65 expected, observed/expected ratio (o/e) 0.21, 90% interval 0.15 to 0.3. The synonymous counts are far from expectation, so gnomAD's model fits this gene poorly and the ratio says little. Missense variants: 1,305 observed, 1,396.1 expected, observed/expected ratio (o/e) 0.93, 90% interval 0.89 to 0.98. Synonymous variants: 651 observed, 552.96 expected, observed/expected ratio (o/e) 1.18, 90% interval 1.1 to 1.26.
Homologues: Orthologues: chimpanzee ATXN2L (97% identical), dog ATXN2L (97% identical), macaque ATXN2L (97% identical), pig ATXN2L (93% identical), mouse Atxn2l (93% identical), rat Atxn2l (92% identical), guinea pig ATXN2L (89% identical), rabbit ATXN2L (87% identical), tropical clawed frog atxn2l (61% identical), zebrafish atxn2l (40% identical), Drosophila melanogaster Atx2 (23% identical), Caenorhabditis elegans atx-2 (19% identical). Paralogues in human: ATXN2 (40% identical).
Diseases named in the same sentence as ATXN2L in open-access papers:
ATXN2L is named in the same sentence as 30 diseases in open-access papers, as found by Europe PMC text mining. Sharing a sentence is not in itself a finding about the gene and the disease. The quoted sentences say what the papers report.
gastric cancer (9 papers, 2019 to 2025). A primary or metastatic malignant neoplasm involving the stomach. "For example, in gastric cancer, ATXN2L expression is upregulated by EGF, which activates the PI3K/AKT signaling pathway, promoting epithelial-mesenchymal transition (EMT), migration, and invasion, all associated with a poor prognosis in gastric cancer." (PMID 39039334, 2024). "In contrast, in oxaliplatin-treated gastric cancers, ATXN2L is involved in Schwann cell assembly, contributing to drug resistance, recurrence, and disease progression in gastric cancer." (PMID 39039334, 2024). "For example, Lin’s study showed ATXN2L upregulated by epidermal growth factor promotes gastric cancer cell invasiveness." (PMID 33776902, 2021). "On the other hand, increased invasion of gastric cancer cells can occur in response to oxaliplatin through ATXN2L up-regulation, known as the regulator of SGs, with the effect of EGF along with the PI3 / AKT signaling pathway." (PMID 34604242, 2021). "ATXN2L may be involved in stress-related malignant activities of cancer, promoting cell invasiveness and can also be an indicator of gastric cancer." (PMID 41462986, 2025). "Notably, we have previously reported that upregulation of the SGs regulator ATXN2L promotes SGs assembly, thus reducing the sensitivity of gastric cancer cell to oxaliplatin." (PMID 37179344, 2023). "In addition, ATXN2L expression was upregulated by epidermal growth factor which promotes gastric cancer cell invasion and drug resistance." (PMID 36412907, 2022). "ATXN2L, as an SG component, contributed to the recurrence and development of Gastric Cancer (GC), even when treated with Oxaliplatin." (PMID 35004322, 2021). "In gastric cancer cell, epidermal growth factor (EGF) regulates the expression of ATXN2L through the PI3K/Akt signaling pathway, thereby increasing the formation of SGs." (PMID 37179344, 2023). "EGF can promote Ataxin-2-like (ATXN2L) as a stress granule regulator in the PI3/AKT signaling pathway, leading to oxaliplatin resistance and eventually increased cell invasion in gastric cancer." (PMID 35004322, 2021). "In addition, ATXN2L promotes cell invasiveness and oxaliplatin resistance and can be upregulated by EGF via PI3K/Akt signaling in gastric cancer." (PMID 35122570, 2022).
Obesity (3 papers, 2013 to 2023). Accumulation of substantial excess body fat. "The “obesity-related” gene group contains MC4R, ATXN2L, GHRL (OR 1.99, P = 8.0×10− 4) and HESX1 (OR 0.23, P = 2.6×10− 3)." (PMID 37292813, 2023). "Among the new discovered loci, ATXN2L, NEGR1 and SH2B1 have also shown a relationship with obesity." (PMID 24267414, 2013).
spinocerebellar ataxia (3 papers, 2016 to 2022). "Ataxin type 2 associated protein encoded by the ATXN2L gene is a member of the spinocerebellar ataxia (SCA) family associated with neurodegenerative diseases." (PMID 36002455, 2022).
type 2 diabetes (3 papers, 2016 to 2025). "For the third example, the effective allele of IBD, BMI, asthma, and type 2 diabetes and intelligence, rs8062405-G decreased the expression of ATXN2L-211." (PMID 36002455, 2022). "ATXN2L contributes to diabetic peripheral neuropathy, the onset of type 2 diabetes in young people and may be a promising therapeutic target for diabetic retinopathy." (PMID 41462986, 2025).
asthma (2 papers, 2022). "ATXN2L, located in the exon boundary and corresponding to cg17992705, is associated with forced vital capacity, a lung function parameter that is reduced in asthma patients." (PMID 36114581, 2022).
spinocerebellar ataxia type 2 (2 papers, 2012 to 2017). A subtype of type I autosomal dominant cerebellar ataxia (ADCA type I) characterized by truncal ataxia, dysarthria, slowed saccades and less commonly ophthalmoparesis and chorea. "The ATXN2L protein is a paralog of ataxin-2 which has been implicated in the neurodegenerative disorder spinocerebellar ataxia type 2." (PMID 29262599, 2017). "For the disease-causing protein in spinocerebellar ataxia type 2, ataxin-2, a paralog of unknown function, termed ataxin-2-like, has been described." (PMID 23209657, 2012).
T-cell lymphoma (2 papers, 2017 to 2025). "ATXN2L has been shown to be widely expressed in immortalized cell lines and in CD4-positive T-cell lymphomas." (PMID 41462986, 2025).
adrenocortical carcinoma (1 paper, 2021). "Atxn2l is a stress response molecule which has been identified as a potential cancer prognosis gene for cancer, such as adrenocortical carcinoma." (PMID 34315405, 2021).
allergic rhinitis (1 paper, 2022). Inflammation of the nasal mucous membranes caused by an IgE-mediated response to external allergens. "HCP5/miR-16/ATXN2L are associated with regulatory T-cell differentiation and function, and regulated IL-13-induced inflammatory cytokine and mucus production in allergic rhinitis." (PMID 35122570, 2022).
Allergy (1 paper, 2022). An allergy is an immune response or reaction to substances that are usually not harmful. "The biological function of ATXN2L, a gene known to be directly related to allergic diseases, was found to be associated with decreased allergy risk in a genome-wide association study (GWAS)." (PMID 35122570, 2022).
amyotrophic lateral sclerosis (1 paper, 2026). Amyotrophic lateral sclerosis (ALS) is a neurodegenerative disease characterized by progressive muscular paralysis reflecting degeneration of motor neurons in the primary motor cortex, corticospinal tracts, brainstem and spinal cord. "Together with its paralog Ataxin-2-like (ATXN2L), both proteins have received much interest, since the deletion of their yeast and fly orthologs alleviates TDP-43-triggered neurotoxicity in Amyotrophic Lateral Sclerosis models." (PMID 41683920, 2026).
autism spectrum disorder (1 paper, 2022). A spectrum of developmental disorders that includes autism, and Asperger syndrome. "Similarly, microduplication of 16p11.2 comprising ATXN2L, TUFM, SH2B1, and ATP2A1 genes can lead to the onset of microcephaly and autism spectrum disorder." (PMID 35722491, 2022).
autoimmune disease (1 paper, 2023). A disorder resulting from loss of function or tissue destruction of an organ or multiple organs, arising from humoral or cellular immune responses of the individual to their own tissue constituents. "This locus maps to the ATXN2L gene which is known to be associated with intelligence, brain morphology, and autoimmune disease." (PMID 36778480, 2023).
colitis (1 paper, 2022). Inflammation of the colon. "For example, in the ATXN2L locus having multiple eQTL/i-rQTL effects for multiple genes, the eQTL effect on IL27 could be responsible for IBD, because the anti-inflammatory roles of IL-27 have been established in a murine colitis model." (PMID 36002455, 2022).
diabetes (1 paper, 2024). "We identify monogenic diabetes variants in 2.4% of individuals and three exome-wide significant (P < 2.6 × 10−6) gene-level associations (HNF1A, MC4R, ATXN2L)." (PMID 38278947, 2024). "For the gene-level associations, all but the ATXN2L association (odds ratio (OR) 1.26, 95% confidence interval 1.15–1.39, P = 1.1 × 10−6, combined minor allele frequency (MAF) 0.36 for 73 variants) have been previously reported as being associated with diabetes." (PMID 38278947, 2024).
Stroke (1 paper, 2021). Sudden impairment of blood flow to a part of the brain due to occlusion or rupture of an artery to the brain. "Finally, in the comparison between MCAO-Ngb and MCAO, which demonstrates the effects of the treatment with Ngb-NPs in animals submitted to stroke, the most evident changes involved overexpression of ATXN2l, FBXO7, and NTRK2." (PMID 35008673, 2021).
cancer (9 papers, 2017 to 2025). A tumor composed of atypical neoplastic, often pleomorphic cells that invade other tissues. "In particular, cancer patients with IDR mutations exhibited even higher expression of ATXN2L than patients with mutations outside IDRs or wild types." (PMID 35061901, 2022). "In tumor tissue, ATXN2L was markedly overexpressed, and the frequency of this overexpression rose as the cancer's stage advanced." (PMID 38922530, 2024). "A previous study has demonstrated that ATXN2L upregulated by epidermal growth factor promotes cancer cell invasiveness and oxaliplatin resistance." (PMID 35061901, 2022). "We found that ATXN2L was significantly upregulated in cancer (P = 1.9E−22), suggesting its oncogenic role." (PMID 35061901, 2022). "To find out the expression status of ATXN2L in GC, we analyzed GC data from The Cancer Genome Atlas dataset, which included 27 pairs of cancer and adjacent noncancerous tissue." (PMID 30787271, 2019). "Current study is the first one that unveiled the prognostic significance of ATXN2L expression in cancer, which was then identified as invasion promotion and chemoresistance acquisition in our cellular biological experiments." (PMID 30787271, 2019). "The frequency of ATXN2L high expression increased along with progression of cancer stage." (PMID 30787271, 2019). "In this study, we discovered the novel functions of ATXN2L in cancer." (PMID 30787271, 2019). "Considering the close relationships between SG and cancer development, we hypothesized that ATXN2L might participate in stress-related cancer malignant activities, which probably implies chemoresistance and EGFR signaling." (PMID 30787271, 2019). "Moreover, we also proved that ATXN2L was necessary for SG assembly under oxaliplatin treatment, which was another compensative process accommodating cancer cells to critical stresses." (PMID 30787271, 2019). "Hence, we wanted to explore the functions of ATXN2L to see whether it participates in stress-related cancer malignant activities." (PMID 30787271, 2019). "However, apart from these limited clues, the function of ATXN2L in cancer remained greatly unknown." (PMID 30787271, 2019). "Ataxin-2-like (ATXN2L) was discovered as a novel regulator of stress granules, yet its function in cancers remained unknown." (PMID 30787271, 2019). "Additionally, we found that ATXN2L was only present in cancer exosomes and absent in non-cancer exosomes." (PMID 38529947, 2024).
neurodegenerative disease (3 papers, 2020 to 2025). A disorder of the central nervous system characterized by gradual and progressive loss of neural tissue and neurologic function. "Overall, this essential role of ATXN2L for embryogenesis raises questions about its role in neurodegenerative diseases and neuroprotective therapies." (PMID 32698485, 2020). "Taken together, this suggests a similar role of atxn2l in zebrafish as well, highlighting its special role as a potential model organism for non-neuronal and neurodegenerative diseases such as ALS and SCA2 and as a neuroprotective therapy model." (PMID 41462986, 2025).
ATXN2L also shares sentences with these, for which no sentence is quoted: tumor (2 papers); Alzheimer disease (1); atherosclerosis (1); bladder urothelial carcinoma (1); breast carcinoma (1); cervical cancer (1); diabetic retinopathy (1); Fanconi anemia (1); metabolic disorders (1); microcephaly (1); neurological diseases (1); theileriasis (1).